NUDT9P1 (nudix hydrolase 9 pseudogene 1)
Synonyms: MGC34007; bA56M3.1; formerly C10orf98
Gene: Processed pseudogene on chromosome 10 (91,152,605 to 91,153,349, reverse strand). Ensembl gene ENSG00000234043.
Diseases named in the same sentence as NUDT9P1 in open-access papers:
NUDT9P1 is named in the same sentence as 1 disease in open-access papers, as found by Europe PMC text mining. Sharing a sentence is not in itself a finding about the gene and the disease. The quoted sentences say what the papers report.
tumor (1 paper, 2023). "Six genes CCSER2, AGAP11, IFIT2, PAPSS2, PCGF5, and NUDT9P1 were observed to have potential NB tumor suppressor activity since their low expression was associated with poor survival even after correction for confounding by other prognostic factors (MYCN status, age at diagnosis, stage of disease)." (PMID 37046696, 2023).